CYP2E1 (cytochrome P450 family 2 subfamily E member 1)
Diseases named in the same sentence as CYP2E1 in open-access papers (continued):
Sharing a sentence is not in itself a finding about the gene and the disease.
hepatocellular carcinoma (29 papers, 2006 to 2025). A malignant tumor that arises from hepatocytes. "Clinically, cytochrome P450 variants CYP3A and CYP2E1 could induce hepatocellular carcinoma and nasopharyngeal carcinoma, respectively." (PMID 34288959, 2021). "Interestingly, treatment with TA attenuated MSG-induced upregulation of Aurora kinase A (Aurka) and Cyclin B2 (Ccnb2), and downregulation of Coagulation Factor IX (F9) and Cytochrome P450 2E1 (Cyp2e1) gene expressions, in which these genes are hepatocellular carcinoma-associated key genes." (PMID 39925850, 2025). "The aim of this meta-analysis was to evaluate the association of ALDH2 rs671 and CYP2E1 rs2031920 polymorphisms with hepatocellular carcinoma (HCC) susceptibility in East Asians." (PMID 31987047, 2020). "Among these, individuals with the CYP2E1 C1/C1 genotype have been found to exhibit an increased risk of hepatotoxicity, particularly in cases of DILI and hepatocellular carcinoma (HCC)." (PMID 41323558, 2025). "In order to do so, we employed commercially available human hepatoma cells and derivatives that have been stably transfected to express CYP2E1 or ADH." (PMID 36358315, 2022). "The cytostatic effect of the new CYP2E1 inhibitor, I-ol, on hepatocellular carcinoma progression is mainly mediated by the cell-cycle regulator, p27." (PMID 33604316, 2021). "The role of CYP2E1 in the development of hepatocellular carcinoma (HCC), the final complication of FLD, remains controversial." (PMID 33604316, 2021). "Herein, CYP2E1 activity and content were determined in fibrotic liver tissue from patients with hepatocellular carcinoma." (PMID 29348818, 2017). "In order to understand the consequences of decreased CYP2E1 in hepatocarcinogenesis, we tested the effect of CYP2E1 levels on hepatoma cell growth." (PMID 25238230, 2014). "Result showed that E47 cells demonstrated significantly lower growth rate compared to C34 cells, indicating that the decreased expression of CYP2E1 promotes hepatoma cell growth." (PMID 25238230, 2014). "We found that ectopic overexpression of HBx inhibits CYP2E1 gene expression via downregulating HNF4α in cultured HepG2 cells and promotes hepatoma cell growth." (PMID 25238230, 2014). "Together, HBx inhibits human CYP2E1 gene expression via downregulating HNF4α which contributes to promotion of human hepatoma cell growth." (PMID 25238230, 2014). "We determined the functional significance of the CYP2E1 regulatory regions through measuring the expression of CYP2E1 in human hepatoma cell lines." (PMID 22815852, 2012). "Importantly, CYP2E1 is one of the core factors involved in alcohol detoxification, and increased CYP2E1 activity correlates with increased susceptibility to DEN-induced hepatocellular carcinoma." (PMID 39908263, 2025). "Also, Nrf2-dependent heme oxygenase 1 (HO-1) expression was induced in CYP2E1-overexpressing HepG2 cells, and contributed to ferroptosis resistance in hepatocellular carcinoma cells by modifying iron metabolism and lipid peroxidation." (PMID 36993697, 2023). "Human hepatoma cells which were stably transfected to express alcohol dehydrogenase (ADH) or cytochrome P4502E1 (CYP2E1) were exposed to EtOH in the absence/presence of inhibitors of ADH (4-methylpyrazole) or CYP2E1 (chlormethiazole)." (PMID 36358315, 2022). "As overexpression of CYP2E1 dramatically inhibits hepatoma cell growth, our observation implies that down-regulation of CYP2E1 during chronic HBV infection may promote hepatocarcinogenesis." (PMID 25238230, 2014). "CYP2E1 overexpression generated oxidative stress in a human hepatoma cell line and induced cytotoxicity to the cells, and CYP2E1 induction could alter immune system responses, leading to increased susceptibility to viral infection." (PMID 25134417, 2014). "Induced CYP2E1 was found to cause oxidative stress by depleting the intracellular GSH levels, activation of the p38 MAP kinase pathway, and induction of the transcription factor Nrf2, in human hepatoma cell line-HepG2." (PMID 21445290, 2011).
hepatocellular carcinoma (continued). "The liver-selective pro-hepatotoxin diethylnitrosamine (DEN) can be metabolized by CYP2E1 to become genotoxic, resulting in hepatocyte apoptosis and tissue damage that can progress to cirrhosis and hepatocellular carcinoma (HCC)." (PMID 36497425, 2022). "The bioactivation of several pre-carcinogens by CYP2E1 has been discussed in relation to the development of cancers, particularly hepatocellular carcinoma (HCC)." (PMID 34360999, 2021). "Recently, down-expression of CYP2E1 was found in hepatocellular carcinoma (HCC) with the majority to be chronic hepatitis B virus (HBV) carriers." (PMID 25238230, 2014). "Furthermore another study detected gene expression of CYP2E1, including CYP1A1/1A2 in PBMC and the liver from human patients with hepatocellular carcinoma." (PMID 36461118, 2022). "Induction of the CYP2E1 enzyme either by alcohol or high-fat diet leads to increased severity of liver pathology and likelihood to develop ALD and NASH, with subsequent influence on the occurrence of hepatocellular cancer." (PMID 34360999, 2021). "We have shown E47 cells with CYP2E1 expression have a significantly lower growth rate compared to C34 cells without ectopic CYP2E1 gene, suggesting that decreased CYP2E1 promotes hepatoma cells growth." (PMID 25238230, 2014). "Furthermore, human hepatoma cells C34, which do not express CYP2E1, shows enhanced cell growth rate compared to E47, which constitutively expresses CYP2E1." (PMID 25238230, 2014). "For example, CYP2E1 expression is higher in breast tumors, in the MGC-803 human gastric cancer cell line, in the esophageal mucosa of patients with esophageal squamous cell carcinoma, and in adjacent nontumor tissues from hepatocellular carcinoma patients, than in their normal counterparts." (PMID 36993697, 2023).
liver fibrosis (28 papers, 2012 to 2025). "The second aim was to elucidate the potential underlying mechanism(s) by which CYP2E1 promotes liver fibrosis." (PMID 28051126, 2017). "Currently both NOX1 and NOX4 and CYP2E1 are implicated in development of inflammation and liver fibrosis, whereas pharmacological inhibitors of these enzymes have been shown in vivo to prevent hepatocyte death and attenuate fibrosis progression." (PMID 27200149, 2016). "However, it is unknown whether CYP2E1 is involved in the liver fibrosis caused by HFD containing cholesterol." (PMID 28051126, 2017). "The data underscore that CYP2E1-facilitated oxidative stress can act as a secondary mechanism by which INH indirectly contributes to hepatic fibrosis via activation of stellate cells and stimulation of collagen production." (PMID 41323558, 2025). "Here, we also demonstrated that antioxidant NAC reverses profibrotic activation of HSC after engulfment of HIV+AGS-induced AB, indicating the role of CYP2E1-generated ROS in liver fibrosis development." (PMID 36101437, 2022). "Because DEN is mainly metabolized by CYP2E1 and high CYP2E1 activity is correlated with hepatic fibrosis, we investigated the hepatic expression of CYP2E1 mRNA in DEN-treated rats." (PMID 32121064, 2020). "Quantitative RT-PCR analysis showed a significant decrease in CYP2E1 mRNA in the liver fibrosis control group to 27% of that of the control group." (PMID 29849890, 2018). "MPEO significantly ameliorates the severity of CCl4-induced liver fibrosis through improving the oxidative status and restoring hepatic CYP2E1 expression." (PMID 29849890, 2018). "This is the first demonstration of a common, MHC-restricted CYP2E1 epitope in patients with anesthetic hepatitis and with hepatic fibrosis." (PMID 30305319, 2018). "To achieve liver fibrosis, we used male wild-type (WT) and Cyp2e1-null mice fed a western fast-food (FF) [high-fat high-cholesterol diet, for 2, 12, and 24 wks]." (PMID 28051126, 2017). "Our results suggest that rats with higher CYP2E1 activity exhibited more severe fibrosis, indicating that inhibition of CYP2E1 activity should be able to moderate hepatic fibrosis." (PMID 29348818, 2017). "In the current study, RLTS pretreatment markedly decreased CYP2E1 expression, which implied that the formation of these radicals and ROS were decreased, thereby attenuated liver fibrosis." (PMID 26083117, 2015). "Since CYP2E1-derived ROS are involved in fibrogenesis, the inhibitory effects of antioxidants and CYP2E1 inhibitors on liver fibrosis have been investigated both in vivo and in vitro." (PMID 23577625, 2013). "CYP2E1 plays a key role in the occurrence and progression of liver fibrosis and liver cancer." (PMID 35136014, 2022). "This specific CYP2E1 downregulation in CCl4 hepatic fibrosis was previously reported and may have contributed to a direct attack of CYP2E1 transcript by the reactive CCl4 metabolites leading to its degradation." (PMID 29849890, 2018). "Thus, we aimed to study the role of CYP2E1 in promoting liver fibrosis by high cholesterol-containing fast-food (FF)." (PMID 28051126, 2017). "Whether CYP2E1 directly and/or indirectly, via its permissive action through other factors such as iNOS, promotes the development of liver fibrosis and whether CYP2E1 plays a role in regulating iNOS and CB-1-R warrant further investigation." (PMID 28051126, 2017). "The lack of upregulated CYP2E1 in our current model despite its clear involvement in the development of hepatic fibrosis may echo some of the discrepancies found in the literature about the role of CYP2E1 in mediating NASH in humans." (PMID 28051126, 2017). "This is the first direct demonstration that the activity of CYP2E1 for DEN was significantly increased in human fibrotic liver tissues, that higher CYP2E1 innate activity correlated with hepatofibrosis, and that inhibition of CYP2E1 activity limited liver fibrosis in response to DEN." (PMID 29348818, 2017).
liver fibrosis (continued). "Importantly, inhibition of CYP2E1 in hepatocytes with low molecular weight compounds is regarded as a promising strategy for prevention/therapy of liver fibrosis." (PMID 26035647, 2015). "Therefore, the main aim of this study was to examine the hypothesis that CYP2E1 plays a role in the progression of NASH to liver fibrosis." (PMID 28051126, 2017). "Experimental studies in animal models and human cell lines strongly support the role of CYP2E1 in promoting lipid peroxidation, GSH depletion, stellate cell activation, and hepatic fibrosis in both acute and chronic settings." (PMID 41323558, 2025). "Carbon tetrachloride (CCl4) is metabolized by CYP2E1 as is APAP and induces liver fibrosis by producing radicals." (PMID 33050213, 2020). "Induction of liver fibrosis by TAA is occurred as a result of its biotransformation, by CYP2E1 enzymes in the liver cells’ microsomes, to a very reactive intermediate known as TAA sulphur dioxide through oxidation." (PMID 31067255, 2019). "Because antisera from the CYP2E1 epitope JHDN-5 induced ROS and mitochondrial oxidative stress in vitro, we hypothesized that JHDN-5 antibodies may positively correlate with hepatic fibrosis in viral hepatitis." (PMID 30305319, 2018). "TC improved Bcl2/Bax ratio, decreased apoptosis, CYP2E1 protein expression and liver fibrosis levels, however, EV offered no such protection." (PMID 29371918, 2017). "In light of all findings, the current study suggest that OBE can evidently inhibit liver fibrosis, which might be related with attenuating oxidative stress, inhibiting α-SMA production, inducing HGF expression and up-regulating CYP2E1 expression." (PMID 26213907, 2015). "Indeed, recent investigations suggested that CYP2E1 induction seems to wane when NASH progresses toward advanced fibrosis, in line with clinical data reporting a significant reduction of CYP2E1 expression with the progression of liver fibrosis." (PMID 36713231, 2023). "This pharmacologic inhibition of NF-kB, JNK and CYP2E1 expression and p38 phosphorylation may contribute to the suppression of α-SMA expression in the liver, leading to attenuation of CCl4-induced liver fibrosis." (PMID 29222479, 2017).
breast carcinoma (25 papers, 2007 to 2025). "Acrylamide is metabolized by cytochrome P450 2E1 (CYP2E1) to the genotoxic epoxide, glycidamide, and is associated with an increased risk for breast cancer." (PMID 39058136, 2024). "Studies of Korean women found a significant interaction for breast cancer risk between rs2031920 (CYP2E1*5) in CYP2E1 and rs671 in ALDH2 and alcohol intake." (PMID 37308906, 2023). "The genetic polymorphic variant CYP2E1 *6 Dra1 (D/C) has also been shown to correlate with higher risk of developing breast cancer and warrants further investigation." (PMID 33809117, 2021). "Odds ratios (ORs) with 95% confidence intervals (CIs) calculated in fixed or random-effects models were used to estimate the strength of the associations between three polymorphisms of CYP2E1 and breast cancer susceptibility." (PMID 28074086, 2017). "explored the relationship of CYP2E1 mutation and breast cancer risk in both CYP2E1*5 and CYP2E1*6 polymorphisms, and were treated independently." (PMID 28074086, 2017). "Nevertheless, the power of a single study was too small to draw a precise conclusion, we therefore investigated breast cancer and CYP2E1 polymorphisms in these common mutations using a meta-analysis." (PMID 28074086, 2017). "CYP2E1 polymorphisms have been reported to influence individual’s breast cancer susceptibility as a phase I enzyme, but the results of these previous studies remain controversial." (PMID 28074086, 2017). "CYP2E1 is also induced by alcohol consumption, which is another risk factor for breast cancer." (PMID 39058136, 2024). "In breast cancer cells, increased CYP2E1 expression is associated with increased ROS levels, suggesting that CYP2E1 may play a role in promoting cancer cell progression, metastasis, and stage advance." (PMID 37370449, 2023). "Finally, we showed that increased expression of the human enzymes that form IS (Cyp2E1, Sult1A1, and Sult1A2) is associated with better survival in breast cancer, an effect that is lost in triple negative cases." (PMID 33050543, 2020). "Consequently, night case–control studies focus on three CYP2E1 polymorphisms (rs2031920 C>T, CYP2E1*5 Rsa I/Pst I and CYP2E1*6 Dra I) and breast cancer risk were included in our meta-analysis." (PMID 28074086, 2017). "The loss of CYP2E1 in CMTs is in line with these findings in human breast cancer." (PMID 25955013, 2015). "Another contributor of ROS in breast cancer cells is the expression of CYP2E1, which increased significantly in breast tumors and adjacent tissues." (PMID 38982523, 2024). "CYP2E1 also regulates autophagy, stimulates stress in the endoplasmic reticulum, and suppresses the metastatic potential of breast cancer cells, indicative of the protective role of CYP2E1." (PMID 38982523, 2024). "The effects of Cyp2E1 expression on survival in breast cancer were analyzed by kmplot.com, a freely accessible database." (PMID 33050543, 2020). "Mammary tissues and breast cancer cells normally metabolize alcohol by CYP2E1, ADH, xanthine oxidoreductase (XOR), and NOX which produces ROS, causing oxidative stress." (PMID 30611309, 2019). "The present study presents a novel mechanism by which the dietary carcinogen PhIP can upregulate CYP2E1 expression, which consequently promotes oxidative stress in breast carcinoma cells." (PMID 29362861, 2018). "CYP2E1, a feature gene in this pathway, was reported to inhibit cell migration in breast cancer cell lines on ectopic expression." (PMID 28212608, 2017). "Since intracellular ROS levels are closely linked to the regulation of autophagy, we followed the autophagy biomarkers beclin-1, LC-3, Atg7 and Atg5 protein levels in breast cancer cells in which the CYP2E1 was either ectopically expressed or silenced." (PMID 24207099, 2013). "In accord with published evidence indicating that CYP2E1 is a positive regulator of UPR, our results lent support to the notion that CYP2E1 induces UPR in MCF7 breast cancer cells transfected with CYP2E1." (PMID 24207099, 2013).
breast carcinoma (continued). "Our results provided evidence that CYP2E1 expression in breast cancer cells plays a role in the determination of migratory capacity." (PMID 24207099, 2013). "Western blot analysis of the autophagic markers in MDA-MB-231 cells lent support to the notion that autophagy is regulated by CYP2E1 in MDA-MB-231 breast cancer cells." (PMID 24207099, 2013). "Ectopic expression of CYP2E1 in breast cancer cells increase ROS generation, modulates autophagy and regulates ER stress and unfolded protein response in a cell-type-dependent manner." (PMID 24207099, 2013). "For example, for the GSTM1-CYP2e1 locus pair at 1 KBP in the second breast cancer study, the common over-represented keywords for the MeSH vocabulary are: "cyp2e1", "ethanol", "smoke", "area", "stomach"', "toxicity", and "xenobiotics"." (PMID 19208188, 2009). "This study investigated the susceptibility and prognostic implications of the CYP2E1, CYP2C19, CYP2D6, mEH and NAT2 gene polymorphisms in breast carcinoma patients." (PMID 18423013, 2008). "Several other large studies, however, indicate that SNPs in ADH1B, ADH1C, and CYP2E1 do not modify associations of alcohol intake with breast cancer risk." (PMID 37308906, 2023). "In addition, CYP2E1 expression in breast cancer cells plays a role in the migratory capacity, autophagy, ER stress and metastasis." (PMID 30611309, 2019). "CYP2E1 expression and activity are reported to play an important role in mammary carcinogenesis and provide a link between ethanol metabolism and progression of breast cancer." (PMID 29362861, 2018). "Our data show that PhIP can regulate CYP2E1-mediated oxidative stress, and the question arises whether these cellular affects could play a role in the initiation or progression of PhIP-induced mammary cancer." (PMID 29362861, 2018). "Since CYP2E1 overexpression restrains migration in the invasive MDA-MB-231 cells, manipulation of CYP2E1 cellular levels could potentially be beneficial for better outcome of late stages of breast cancer." (PMID 24207099, 2013). "The results shown in this manuscript suggest that manipulation of CYP2E1 protein levels and enzymatic activity could be potentially exploited in breast cancer therapy." (PMID 24207099, 2013). "These previous findings are in accordance with ours which demonstrate the absence of any association between CYP2C19 and CYP2E1 gene polymorphisms with breast cancer." (PMID 18423013, 2008). "Interestingly, CYP2E1-induced ROS generation influences migration in breast cancer cells, thus may be involved in breast cancer metastasis." (PMID 35582590, 2019). "However, this is highly speculative, also due to the fact that we did not see interaction between acrylamide and the CYP2E1 SNPs which leaves the possibility that there may not be a true association between acrylamide intake and breast cancer risk." (PMID 29445914, 2019). "Another important enzyme is cytochrome P450 2E1 (CYP2E1), known to be overexpressed in breast cancer cells and to enhance ROS production." (PMID 26540569, 2015).